MAPK8 (mitogen-activated protein kinase 8)
Description:
Serine/threonine-protein kinase involved in various processes such as cell proliferation, differentiation, migration, transformation and programmed cell death. Extracellular stimuli such as pro-inflammatory cytokines or physical stress stimulate the stress-activated protein kinase/c-Jun N-terminal kinase (SAP/JNK) signaling pathway. In this cascade, two dual specificity kinases MAP2K4/MKK4 and MAP2K7/MKK7 phosphorylate and activate MAPK8/JNK1. In turn, MAPK8/JNK1 phosphorylates a number of transcription factors, primarily components of AP-1 such as JUN, JDP2 and ATF2 and thus regulates AP-1 transcriptional activity. Phosphorylates the replication licensing factor CDT1, inhibiting the interaction between CDT1 and the histone H4 acetylase HBO1 to replication origins. Loss of this interaction abrogates the acetylation required for replication initiation. In T-cells, MAPK8 and MAPK9 are required for polarized differentiation of T-helper cells into Th1 cells. Contributes to the survival of erythroid cells by phosphorylating the antagonist of cell death BAD upon EPO stimulation. Mediates starvation-induced BCL2 phosphorylation, BCL2 dissociation from BECN1, and thus activation of autophagy. Phosphorylates STMN2 and hence regulates microtubule dynamics, controlling neurite elongation in cortical neurons (By similarity). In the developing brain, through its cytoplasmic activity on STMN2, negatively regulates the rate of exit from multipolar stage and of radial migration from the ventricular zone (By similarity). Phosphorylates several other substrates including heat shock factor protein 4 (HSF4), the deacetylase SIRT1, ELK1, or the E3 ligase ITCH. Phosphorylates the CLOCK-BMAL1 heterodimer and plays a role in the regulation of the circadian clock. Phosphorylates the heat shock transcription factor HSF1, suppressing HSF1-induced transcriptional activity. Phosphorylates POU5F1, which results in the inhibition of POU5F1's transcriptional activity and enhances its proteasomal degradation (By similarity). Phosphorylates JUND and this phosphorylation is inhibited in the presence of MEN1. In neurons, phosphorylates SYT4 which captures neuronal dense core vesicles at synapses (By similarity). Phosphorylates EIF4ENIF1/4-ET in response to oxidative stress, promoting P-body assembly. Phosphorylates SIRT6 in response to oxidative stress, stimulating its mono-ADP-ribosyltransferase activity. Phosphorylates NLRP3, promoting assembly of the NLRP3 inflammasome. Phosphorylates ALKBH5 in response to reactive oxygen species (ROS), promoting ALKBH5 sumoylation and inactivation. JNK1 isoforms display different binding patterns: beta-1 preferentially binds to c-Jun, whereas alpha-1, alpha-2, and beta-2 have a similar low level of binding to both c-Jun or ATF2. However, there is no correlation between binding and phosphorylation, which is achieved at about the same efficiency by all isoforms.
Synonyms: SAPK1c; JNK1; PRKM8; SAPK1; JNK; JNK-46; JNK1A2; JNK21B1/2
Tractability: Small molecule: a drug acting on it is in phase 2 or 3 trials; a structure with a bound ligand is known; a high-quality ligand is known; it has a high-quality binding pocket; it belongs to a druggable protein family. PROTAC: it is named in the literature on targeted protein degradation; ubiquitination databases record sites on it; its protein half-life has been measured; a small molecule that binds it is known.
Target class: Protein Kinase; CMGC protein kinase JNK subfamily; Enzyme; Kinase; CMGC protein kinase group; CMGC protein kinase MAPK family
Chemical probes: JNK-IN-7 (high quality), PD083058
Gene: Protein-coding gene on chromosome 10 (48,306,639 to 48,439,360, forward strand). Ensembl gene ENSG00000107643.
Subcellular location: Cytoplasm; Nucleus; Synapse
Subcellular location (Human Protein Atlas): Nucleoplasm
Pathways (Reactome):
Immune System: Activation of the AP-1 family of transcription factors; FCERI mediated MAPK activation; Interleukin-38 signaling; JNK (c-Jun kinases) phosphorylation and activation mediated by activated human TAK1
Disease: Signaling by ALK fusions and activated point mutants; WNT5:FZD7-mediated leishmania damping
Programmed Cell Death: Activation of BIM and translocation to mitochondria; Activation of BMF and translocation to mitochondria
Signal Transduction: NRAGE signals death through JNK; NRIF signals cell death from the nucleus
Cellular responses to stimuli: Oxidative Stress Induced Senescence
DNA Repair: Recruitment and ATM-mediated phosphorylation of repair and signaling proteins at DNA double strand breaks
Gene Ontology:
Molecular function: enzyme binding; histone deacetylase binding; histone deacetylase regulator activity; JUN kinase activity; protein binding; protein phosphatase binding; protein serine kinase activity; protein serine/threonine kinase activity; protein serine/threonine kinase binding; ATP binding; MAP kinase activity; protein kinase activity
Biological process: cellular response to amino acid starvation; cellular response to lipopolysaccharide; cellular response to mechanical stimulus; cellular response to oxidative stress; cellular response to reactive oxygen species; JNK cascade; JUN phosphorylation; MAPK cascade; negative regulation of apoptotic process; negative regulation of protein binding; peptidyl-serine phosphorylation; peptidyl-threonine phosphorylation; positive regulation of cyclase activity; positive regulation of gene expression; positive regulation of NLRP3 inflammasome complex assembly; positive regulation of protein metabolic process; protein phosphorylation; regulation of protein localization; response to oxidative stress; response to UV; stress-activated MAPK cascade; cellular senescence; energy homeostasis; Fc-epsilon receptor signaling pathway; positive regulation of apoptotic process; and 5 more
Cellular component: nucleoplasm; nucleus; axon; basal dendrite; cytoplasm; cytosol; synapse
Genetic constraint (gnomAD): Loss-of-function variants: 9 observed, 29.54 expected, observed/expected ratio (o/e) 0.3, 90% interval 0.18 to 0.53. The upper end of that interval is the gene's LOEUF score, 0.53, which puts it in group 2 of 6, group 1 being the genes least tolerant of losing a copy. Missense variants: 207 observed, 388.25 expected, observed/expected ratio (o/e) 0.53, 90% interval 0.47 to 0.6. Synonymous variants: 138 observed, 128.82 expected, observed/expected ratio (o/e) 1.07, 90% interval 0.93 to 1.23.
Homologues: Orthologues: chimpanzee MAPK8 (99% identical), pig MAPK8 (99% identical), guinea pig MAPK8 (97% identical), rabbit MAPK8 (97% identical), rat Mapk8 (97% identical), mouse Mapk8 (97% identical), tropical clawed frog mapk8 (93% identical), macaque MAPK8 (87% identical), zebrafish mapk8a (87% identical), zebrafish mapk8b (77% identical), Caenorhabditis elegans kgb-1 (43% identical), Caenorhabditis elegans kgb-2 (39% identical), and 9 more. Paralogues in human: MAPK10 (91% identical), MAPK9 (81% identical), MAPK14 (42% identical), MAPK11 (41% identical), MAPK12 (39% identical), MAPK13 (39% identical), MAPK7 (36% identical), MAPK1 (34% identical), MAPK3 (33% identical), MAPK15 (30% identical), NLK (30% identical), MAPK6 (28% identical), and 7 more.
Diseases named in the same sentence as MAPK8 in open-access papers:
MAPK8 is named in the same sentence as 654 diseases in open-access papers, as found by Europe PMC text mining. Sharing a sentence is not in itself a finding about the gene and the disease. The quoted sentences say what the papers report.
Insulin resistance (537 papers, 2008 to 2026). Increased resistance towards insulin, that is, diminished effectiveness of insulin in reducing blood glucose levels. "Loss of FUNDC1-mediated mitophagy was demonstrated to increase insulin resistance through inducing adipose tissue-associated macrophage infiltration and hyperactivation of mitogen-activated protein kinase 8 (MAPK8, also named JNK1)." (PMID 32235615, 2020). "MAPK8 activation in adipose tissue can cause insulin resistance in the liver." (PMID 20419126, 2010). "MAPK8 is known as the c-Jun NH2-terminal kinase 1 (JNK1), and is involved in the mechanism of obesity-induced insulin resistance." (PMID 25144649, 2014). "The inhibition of TLR2 expression can rescue cells from the activation of MAPK8 and improve insulin resistance." (PMID 23213270, 2012). "Moreover, the decrease in proteins like MAPK8 indicates a weakening of the stress-activated pathways that play a role in insulin resistance, a fundamental aspect of metabolic syndrome." (PMID 38794679, 2024). "Moreover, MAPK8 plays an essential role in the development of insulin resistance and obesity, whereas MAPK8 knockout mice displayed improved adiposity and insulin sensitivity." (PMID 36386135, 2022). "Specifically, regarding genes related to insulin resistance pathway, we highlight SOCS3, GSK3B, STAT3, PTEN, TRIB3, FOXO1, and PTPRF, along with MAPK8, which plays a role in metabolic stress and inflammation." (PMID 41282288, 2025). "IR-induced ER stress leads to MAPK8 hyperactivation, which phosphorylates and inhibits IRS-1, resulting in systemic insulin resistance.ER stress-alleviators reduce hyperglycemia and systemic IR in obese diabetic mice." (PMID 41567335, 2025). "Genes with higher degree including VEGFA, PTGS2, JUN, MAPK8, and HSP90AA1 are hub genes of TwHF against DKD, which are involved in inflammation, insulin resistance, and lipid homeostasis." (PMID 33274236, 2020). "JNK activity has been associated with obesity in a mouse model, where the absence of JNK1 (MAPK8), a protein in the same family as MAPK10, protects against the obesity-induced insulin resistance." (PMID 24278029, 2013).
breast cancer (307 papers, 2006 to 2026). A primary or metastatic malignant neoplasm involving the breast. "We observed that inactivation of JNK signalling, along with low expression of MAP2K7 and MAPK8, were consistently associated with poor outcome or poor drug response in ER+ breast cancer following various treatment regimes." (PMID 40826108, 2025). "MAPK8 (JNK, c-Jun N-terminal kinase) in our study has been associated with breast-cancer risk at rs10857561, both in the individual main and hormone-receptor positive (ER + and PR +) stratified analyses, as well as in the SNP-SNP interaction analyses." (PMID 37789226, 2023). "While rs10857561 in MAPK8 showed noteworthy risk estimates for breast cancer in general as well as ER-positive and PR-positive subgroups in our analyses, this SNP has been previously shown to be associated with rectal cancer once more highlighting the role in carcinogenesis." (PMID 37789226, 2023). "The observed interactions between genetic variants of TPH2 and MAPK8 highlight their cooperation as putative breast-cancer risk modulators and call upon the comprehensive scrutiny of the circadian clock system and its input and output effectors in large breast-cancer cohorts." (PMID 37789226, 2023). "MAPK8 signaling plays a multifunctional role in breast cancer, influencing tumor progression, metastasis, therapy resistance, and stem cell regulation." (PMID 40468448, 2025). "We validated the function of the predicted kinases using RNAi-based screening and identified the IKBKE and MAPK8 kinases as mechanoregulated proteins being potential targets for development of novel breast cancer treatment." (PMID 40468448, 2025). "Knockdown of MAPK8 using an siRNA-pool significantly inhibited the invasive breast cancer phenotype and cell proliferation in CA1a human breast cancer cells." (PMID 40468448, 2025). "We developed multiple CRISPR/Cas9 knockout ER+ breast cancer cell lines (MCF-7 and T-47D) to investigate the effects of MAP2K7 and downstream MAPK8 and MAPK9 loss." (PMID 40826108, 2025). "In conclusion, we show that matrix stiffness activates several tyrosine and serine/threonine kinases and validated two of these kinases, IKBKE and MAPK8, as critical for a malignant breast cancer cell phenotype." (PMID 40468448, 2025). "Further studies are therefore needed to elucidate if the effects of JNK-IN-8 in breast cancer cells are specifically due to MAPK8 inhibition." (PMID 40468448, 2025). "Collectively, these findings indicate that matrix stiffness-induced MAPK8 activity promote breast cancer progression and suggest that MAPK8 signaling represents a candidate for the development of new breast cancer treatment modalities." (PMID 40468448, 2025). "ER+ breast cancers with MAPK8 deletions had on average 21.6% lower JNK activity, whereas cancers with MAPK9 deletion had 26.9% lower JNK phosphorylation than those without MAPK9 deletions." (PMID 40826108, 2025). "Clinical trials will be essential to evaluate the efficacy of JNK-IN-8, or other relevant MAPK8 inhibitors, as a potential therapeutic agent for breast cancer." (PMID 40468448, 2025). "In breast cancer, MAPK8 activation enhances the expression of ECM components such as osteopontin and tenascin C, which drive metastasis and therapy resistance by reinforcing the chemoresistant metastatic niche." (PMID 40468448, 2025). "Meanwhile, in breast cancer, the heterotopic expression of miR-193a-3p in cancer cells directly targets mitogen-activated protein kinase 8 (MAPK8), resulting in low CCND1 expression levels." (PMID 32095323, 2020). "As an upstream mediator of FoxO signaling, MAPK8 was suppressed in breast cancer cells (MCF‐7, T47D, ZR‐75, and MDA‐MB‐231) and liver cells (LO2) treated with TAM." (PMID 32508033, 2020). "It was reported that phosphorylated MAPKs including ERK2 (MAPK1), JNK1 (MAPK8) and p38 MAPK (MAPK14) over-expressed in breast cancer patients and is associated with poor prognosis." (PMID 33246450, 2020).
breast cancer (continued). "We confirmed that TAM can function through the MAPK8/FoxO signaling pathway in breast cancer cells (MCF‐7, T47D, ZR‐75, and MDA‐MB‐231) and liver cells (LO2)." (PMID 32508033, 2020). "FAK induces BCAR1 (breast cancer anti-estrogen resistance 1) and MAPK8 mediated cellular motility, proliferation, and survival in breast cancer." (PMID 35582722, 2019). "The involvement of some of the genes affecting cancer cell death–Adm, Cflar, Cyr61, Ddit4, Itgb1, Mapk1, Mapk8, Tgfβ2, Tpm1, Vegfα and Wasf1, was demonstrated in breast cancer cell lines." (PMID 19450255, 2009). "This suggests that IKBKE and/or MAPK8 inhibitors could enhance the arsenal of treatments to prevent or treat breast cancer." (PMID 40468448, 2025). "Despite its established role in ECM remodeling and tumor progression, the possible regulatory links from ECM stiffness to MAPK8 activity in breast cancer remain unclear." (PMID 40468448, 2025). "Furthermore, JNK knockdown decreases ER+ breast cancer cell proliferation, an observation that we also see with MAPK8 or MAPK9 knockdown." (PMID 40826108, 2025). "This suggests that IKBKE and/or MAPK8 inhibitors could play a role in future breast cancer prevention and treatment." (PMID 40468448, 2025). "The triple interaction of TPH2 rs1386483 and rs1473473 as well as RAF1 rs3729931 increased breast-cancer risk by 20%, a dual interaction of MAPK8 rs10857561 and MAP2K1 rs1347069 by 15%, and MAPK8 rs10857561 alone by 11% (all observed at a prior probability of 0.01)." (PMID 37789226, 2023). "The result showed that TAM may induce fatty liver in patients with breast cancer by interfering with the MAPK8/FoxO signaling pathway." (PMID 32508033, 2020). "It is noteworthy that MAPK8 was overexpressed in breast cancer samples compared to normal samples." (PMID 32508033, 2020). "We verified that TAM may induce fatty liver in breast cancer through the MAPK8/FoxO signaling pathway." (PMID 32508033, 2020). "The IKBKE-inhibitor Amlexanox, clinically utilized for aphthous ulcers, as well as the MAPK8 inhibitor JNK-IN-8, reinstalled the DCIS-like phenotype of breast cancer cells on high matrix stiffness." (PMID 40468448, 2025). "Firstly, we examined the expression and phosphorylation of JNK1 (MAPK8) and JNK2 (MAPK9) in ER+ breast cancer using UALCAN data." (PMID 40826108, 2025). "Consistently, our study found that MAPK8 was a DPT of TAM, which induces the apoptosis of breast cancer cells and steatosis in liver cells." (PMID 32508033, 2020). "The expression levels of Prss14/epithin (ST14), PKCβ (PRKCB), and three JNKs (MAPK8, MAPK9, and MAPK10) in more aggressive ER-negative (ER−) and less aggressive ER-positive (ER+) breast cancer patients were compared individually in the plot." (PMID 32241917, 2020). "We found that MAPK8 was one DPT of TAM, and significant genes of breast cancer and fatty liver were correlated with the MAPK and FoxO signaling pathways; the MAPK signaling pathway was found to be upstream of the FoxO signaling pathway." (PMID 32508033, 2020). "In addition, breast cancer patients with high expression of ATAT1 and MAPK8, RASSF1, BCL2, CXCL8, and FGF1, had a poor prognosis." (PMID 34199510, 2021). "Additionally, two individual MAPK8 siRNAs with confirmed knockdown efficiency reversed the stiffness-induced phenotype (top row) and suppressed cell growth proliferation (bottom row) in HCC1143 human breast cancer cells." (PMID 40468448, 2025). "Target prediction, bioinformatics, molecular docking, and molecular dynamics revealed that the most promising hybrid 4a may exert anti-breast cancer activity by acting on multiple targets such as EGFR, PIK3CA, and MAPK8 and thus participating in multiple tumor-related signaling pathways." (PMID 37928644, 2023).
Obesity (296 papers, 2007 to 2026). Accumulation of substantial excess body fat. "In adipose tissue of high fat diet-induced obese rats, MAPK8 is significantly downregulated and apoptosis of adipocytes inhibited, which may be the main contributory factor to obesity." (PMID 33897762, 2021).
hepatocellular carcinoma (181 papers, 2006 to 2026). A malignant tumor that arises from hepatocytes. "In hepatocellular carcinoma tissues, activation of MAPK8 is increased and correlates with poor patient prognosis." (PMID 40369663, 2025).
diabetes (164 papers, 2008 to 2026). "The dysregulation of MAPK8 has also been implicated in several diseases, including diabetes, cancer, autoimmune diseases, cardiac hypertrophy, and asthma." (PMID 37325630, 2023). "Diabetes impairs AMPK activation of MAPK8/JNK1/BCL2 signalling and subsequent BECN1-BCL2 dissociation, promoting apoptosis by suppressing autophagy." (PMID 36267813, 2022). "The effect of CPP extract on various genes such as Pdx-1, Ins-1, ngn-3, GLUT-4, and IRS-1 in insulin signaling pathway and Traf-4, Traf-6, and Mapk-8 in MAPK downstream JNK cascade was examined through qRT-PCR to access the core molecular mechanism involved in CPP-induced recovery of diabetes." (PMID 32256963, 2020). "GCG, IRS1, VEGFA, STAT3, CCL2, CASP3, and APOE as diabetes mellitus-related proteins and SREBF1, LPL, PPARA, APOB, GPT, MAPK8, and FASN as NAFLD-specific proteins were identified as possible discriminating factors between the two studied diseases." (PMID 35154608, 2021). "Another research also reported that diabetes induced apoptosis and suppressed autophagy of cardiomyocytes through inhibiting AMPK, suppressing the MAPK8/JNK1-Bcl-2 signaling pathway, and subsequently promoting the interaction between Beclin-1 and Bcl-2." (PMID 26950124, 2016).
colon carcinoma (156 papers, 2006 to 2025). "No or low expression of MAPK8 protein was detected in colon cancer tissue, while moderate expression was observed in normal tissue." (PMID 41515982, 2025). "They further identified JUN-terminal kinase (JNK)/MAPK8 or TAK1/MAP3K7 as transducing the signal from ERN1 to JUN; the simultaneous inhibition of this pathway and MEK results in synthetic lethality in KRAS-mutant human colon cancer cells." (PMID 38275900, 2024).